RTN3 (reticulon 3)
Diseases named in the same sentence as RTN3 in open-access papers (continued):
Sharing a sentence is not in itself a finding about the gene and the disease.
infection (5 papers, 2020 to 2026). The state of being infected such as from the introduction of a foreign agent such as serum, vaccine, antigenic substance or organism. "A549 cells were infected at a high multiplicity of infection with the A/WSN/33 (WSN) or A/Victoria/3/75 (VIC) virus, fixed at 8 h post-infection (hpi) and stained for the endogenous RTN3 and CLIMP63 proteins, and the viral NP." (PMID 40668844, 2025). "Our recent studies with the hepatitis C virus (HCV)—another positive-strand RNA virus in the Flavivirus family—revealed that RTN3 is upregulated during infection and is incorporated into exosomes carrying infectious viral RNA." (PMID 41012666, 2025). "To further assess the role of RTN3 in attenuating antiviral activities, we transfected HEK293T cells with RTN3 or empty vector and followed by infection with VSV-eGFP." (PMID 34313226, 2021). "Further RT-PCR analyses determined that the levels of IFNB1, IFIT2, IFIT1, TNF and the proinflammatory cytokines CCL20 and IL6 were enhanced by RTN3 knockdown during VSV infection, while the amplification of VSV was compromised." (PMID 34313226, 2021). "Our results demonstrate that RTN3 is upregulated upon infection with VSV or poly(I:C) stimulation and then self-aggregates along the ER membrane." (PMID 34313226, 2021). "As expected, the protein and mRNA levels of RTN3 were both significantly increased by poly(I:C) stimulation or VSV-eGFP infection in A549 cells, with a similar phenomenon observed in THP-1 cells." (PMID 34313226, 2021). "Our observations also suggest that RTN3 represents a novel infection biomarker and therapeutic target that can be exploited to prevent the cellular release of infectious viral exosomes associated with HCV infection." (PMID 32941510, 2020). "There is currently highly effective therapy for HCV infection, hence we assessed the effect of treatment on infection-induced increased RTN3 and infectious exosome release." (PMID 32941510, 2020). "We highlight reticulon-3 (RTN3), an ER-shaping protein, as an upstream regulator that can couple infection-induced ER microdomains to endosomal docking and to autophagy-linked trafficking decisions that bias intermediates toward secretion rather than degradation." (PMID 42117840, 2026). "RTN3-KD infected cells showed only minimal RTN3 transcript levels (down to ~10% of infected controls, p < 0.001), indicating sustained knockdown despite the infection-triggered response." (PMID 41012666, 2025). "Huh7 cells were subjected to RTN3 knockdown (KD) using CRISPR-Cas9 before infection." (PMID 41012666, 2025). "Our discovery of RTN3 as an EV regulator suggests new therapeutic angles: modulation of ER curvature proteins or inhibition of specific cargo-loading domains could attenuate exosome-mediated infection." (PMID 41012666, 2025). "This indicates that RTN3 and NS3 form a complex or are part of the same membrane-bound assemblies during infection." (PMID 41012666, 2025). "(H) CoIP and immunoblot analyses of HEK293T cells transfected with HA-Ub-K63 and Flag-Ev or increasing amounts of Flag-RTN3 (+, ++) together with GFP-RIG-I or GFP-Ev in the indicated groups for 24 hr and followed by infection with VSV (MOI = 1) for 8 hr." (PMID 34313226, 2021). "Further experiments evaluating VSV-eGFP infection in the liver revealed that the VSV-infected cell population was increased in RTN3-overexpressing mice, and the MFI of the GFP signal indicated that VSV-eGFP infection also increased to a certain extent." (PMID 34313226, 2021). "(B) CoIP and immunoblot analysis of HEK293T-shCtrl and HEK293T-shTRIM25 cells transfected with HA-Ub-K63 and increasing amounts of Flag-RTN3 (+, ++) or Flag-Ev together with GFP-RIG-I or GFP-Ev in the indicated groups for 24 hr and followed by infection with VSV (MOI = 1) for 8 hr." (PMID 34313226, 2021).
infection (continued). "Considering that the RTN3 overexpression leads to its aggregation in the ER and may cause nonspecific interactions (such as structural enfolding), we used GFP-TRIM25 to pull down endogenous RTN3 and confirmed its interaction with TRIM25 and that this interaction was strengthened by VSV infection." (PMID 34313226, 2021). "In uninfected cells, RTN3 IP did not bring down NS3 (which is absent), confirming the specificity of the interaction under infection conditions." (PMID 41012666, 2025).
kidney disease (3 papers, 2022 to 2024). "Although our prior research has indicated that a deficiency in Reticulon-3 (RTN3) accelerates renal disease progression, a thorough examination of RTN3 on kidney function and pathology remains underexplored." (PMID 38937317, 2024). "Reticulon 3 (RTN3), an endoplasmic reticulum protein, is crucial in neurodegenerative and kidney diseases." (PMID 36925557, 2023). "Our study may be the first to identify a relationship between the RTN3 gene and kidney diseases." (PMID 35596061, 2022). "However, to date, an association of RTN3 with kidney disease has not been reported." (PMID 35596061, 2022). "However, it has not been established whether RTN3 expression has any effects on kidney disease." (PMID 35596061, 2022).
cardiovascular disease (2 papers, 2023 to 2024). "This study identified RTN3 as a critical driver of HF after MI and suggests targeting RTN3 as a promising therapeutic strategy for MI and related cardiovascular diseases." (PMID 38420163, 2024). "Therefore, targeting RTN3 using AAVs or small molecule inhibitors may be a potential strategy for preventing and treating post‐MI HF and other cardiovascular diseases." (PMID 38420163, 2024). "In addition, previous research has shown that the expression of ferroptosis-related genes (RTN3, SLC25A1, and GPX4) in cardiovascular disease correlates with the serum HDL level." (PMID 38086802, 2023).
metabolic disease (1 paper, 2018). A congenital disorder (due to inherited enzyme abnormality) or acquired (due to failure of a metabolically important organ) disorder resulting from an abnormal metabolic process. "Interestingly, many of the DEGs common in both analyses are connected to metabolic diseases and are considered potential therapeutic targets (e.g., FASN, RTN3)." (PMID 30509175, 2018).
RTN3 also shares sentences with these, for which no sentence is quoted: Traumatic Injury (2 papers); acute lung injury (1); brain disease (1); cognitive deficits (1); colon cancers (1); dementia (1); dilatation (1); fibrosis (1); hypertriglyceridemia (1); idiopathic pulmonary fibrosis (1); insulin-dependent diabetes (1); legionellosis (1); neurological diseases (1); pancreatic neuroendocrine neoplasm (1); Parkinson disease (1); periodontitis (1); primary hypertension (1); rheumatoid arthritis (1); secondary hypertension (1).